CCL2 (C-C motif chemokine ligand 2)
Diseases named in the same sentence as CCL2 in open-access papers (continued):
Sharing a sentence is not in itself a finding about the gene and the disease.
Respiratory distress (1 paper, 2023). Respiratory distress is objectively observable as the physical or emotional consequences from the experience of dyspnea. "Furthermore, higher plasma levels of IL-6, IL-1β, IL-8, CCL2, (among other markers such as TNF-α) and IL-6 were also associated with post-TBI mortality, whereas higher levels of IL-6 and IL-8 were associated with respiratory distress in TBI patients." (PMID 37415924, 2023).
Respiratory tract infection (1 paper, 2022). An infection of the upper or lower respiratory tract. "As CCL2 is integral to bacterial control, yet is reduced during respiratory tract infection with IAV." (PMID 36365071, 2022).
Retinal atrophy (1 paper, 2013). A nonspecific term denoting wasting, especially as a result of degeneration, of the retinal pigment epithelium (RPE) and neurosensory retinal cells. "Since our mice do not have Crb-1 rd8 mutation, our results suggest that the deletion of Ccl2 and Cx3cr1 predisposes mice to retinal atrophy under aging and chronic light damage conditions more so than in the single CCL2 or CCR2 knockout mice." (PMID 23637822, 2013). "All CCL2−/−CX3CR1GFP/GFP mice exposed to extra-light (∼800lux, 6 h/day, 6 months) developed patches of retinal atrophy, and only 20–25% of WT mice which underwent the same light treatment developed atrophic lesions." (PMID 23637822, 2013).
sensorineural deafness (1 paper, 2024). "Ccl2 plays a key role in ototoxic-induced sensorineural deafness and is involved in monocyte migration and activation after hearing injury." (PMID 39764513, 2024).
Sensory neuropathy (1 paper, 2018). Peripheral neuropathy affecting the sensory nerves. "Furthermore, previous research has demonstrated that Ccl2 is upregulated in DRG neurons and microglia following peripheral nerve injury prompting macrophage infiltration and sensory neuropathy." (PMID 29894476, 2018).
severe combined immunodeficiency (1 paper, 2020). Severe combined immunodeficiency (SCID) comprises a group of rare monogenic primary immunodeficiency disorders characterized by a lack of functional peripheral T lymphocytes resulting in early-onset severe respiratory infections and failure to thrive. "Inguinal mammary fat pads of 3-week-old nonobese diabetic/severe combined immunodeficiency (NOD/SCID) mice were cleared of endogenous mammary epithelium and humanized with SVF cells expressing empty vector (SVF/EV) or CCL2 (SVF/CCL2)." (PMID 32731354, 2020).
skin toxicities (1 paper, 2022). "In individuals with EGFRI-induced skin toxicities, the levels of various inflammatory cytokines are increased, including IL6, TNFα, and CCL2." (PMID 35324426, 2022).
somatotropinoma (1 paper, 2019). "NF-PitNETs secreted higher amounts of cytokines/chemokines than somatotropinomas, especially CCL2 (16x more), IL-8 (25x more) and CCL4 (27x more), except for FGF-2 which was found in higher concentrations in somatotropinoma supernatants." (PMID 31703742, 2019). "NF-PitNETs were more often secreting IL-8, CCL2, CCL4, IL-6 and PDGF-AA than somatotropinomas." (PMID 31703742, 2019).
spinal stenosis (1 paper, 2007). Narrowing of the spinal canal. "Indeed, we previously demonstrated that in a rodent model of spinal stenosis, chronic compression of the DRG (CCD), produced a delayed but chronic expression of both the chemokine receptor CCR2 and its ligand, the chemokine MCP-1/CCL2 in lumbar DRGs." (PMID 18076762, 2007).
stenosis (1 paper, 2021). "Both CCR2 and its cognate antigen CCL2/MCP-1 are linked to human arterial stenosis and genetic and pharmacologic disruption of MCP-1/CCR2 signaling effectively suppresses arterial remodeling in animal models." (PMID 34934133, 2021).
tendinopathy (1 paper, 2019). "Coupled with confirmation of passive release of CCL2 in response to acute injury our data supports the concept of S100A8 & A9 acting as functional tissue alarmins in tendinopathy by promoting immune cell recruitment." (PMID 30728384, 2019).
thymoma (1 paper, 2023). A neoplasm arising from the epithelial cells of the thymus. "Based on the TCGA dataset, we also showed that IFN-γ, ICAM1, and TNF expression were decreased in thymoma; however, CCL2 expression was considerably increased." (PMID 37644514, 2023).
thyroid tumor (1 paper, 2022). A benign or malignant neoplasm affecting the thyroid gland. "CXCL8 and CCL2 are two chemokines secreted by thyroid tumor cells." (PMID 35498406, 2022).
tuberculoid leprosy (1 paper, 2014). A principal or polar form of leprosy in which the skin lesions are few and are sharply demarcated. "Of the 24 soluble mediators of inflammation that were measured, 7 showed significant differences between lepromatous and tuberculoid leprosy (CCL2, CCL17, CCL18, IFNA1, IL10, IL22, and TNF)." (PMID 25412496, 2014).
tubular adenoma (1 paper, 2021). A usually polypoid neoplasm arising from the glandular epithelium. "CCL2 was upregulated in the tubular adenomas by 1.4-fold compared with the normal tissue but downregulated in the tubulo-villous and villous adenomas by 1.4- and 5.9-fold, respectively." (PMID 34884259, 2021).
urothelial bladder cancers (1 paper, 2022). "Previous studies validated that CCL2, IL10, CD163, and NRP1 had adverse influence on progression and prognosis of BLCA, while CSF1R antagonist had been used in treatment of urothelial bladder cancers." (PMID 36263004, 2022).
Vestibular schwannoma (1 paper, 2024). A vestibular schwannoma (also known as acoustic neuroma, acoustic neurinoma, or acoustic neurilemoma) is a benign, usually slow-growing tumor that develops from the VIIIth cranial nerve supplying the inner ear. "In addition to CCL2, the examination of our cell culture supernatants of VS primary cultures suggests that vestibular schwannoma cells produce the cytokines CCL5, CCL18, TGFB1, and GDF15, which has not yet been investigated for VSs." (PMID 39272860, 2024).
xerostomia (1 paper, 2024). Dryness of the mouth resulting from reduced salivary secretion. "However, we have not observed any correlation between CCL2 and sicca symptoms, specifically xerostomia and salivary flow." (PMID 38255988, 2024).
tumor (4,049 papers, 1995 to 2026). "Utilizing multiple mouse models, we confirmed that SRSF10 ablation with a selective inhibitor 1C8 robustly inhibits GC growth and enhances CD8+ T-cell infiltration via CCL2-mediated reprogramming of tumor-associated macrophages (TAMs)." (PMID 42020371, 2026). "Consistently, N4BP1-deficient SCC9 and CAL27 tumor tissues exhibited increased CCL2 expression along with increased M1 macrophage marker, iNOS." (PMID 41513619, 2026). "For instance, targeting the CCL2/CCR2 signaling pathway can reprogram tumor-associated macrophages (TAMs), thereby enhancing immune cell infiltration and antitumor immune responses." (PMID 41601632, 2026). "TICs also release cytokines and factors (like TGF-β, IL-10, and CCL2) that change tumor-associated macrophages into M2 cells and attract MDSCs." (PMID 41550427, 2025). "The elevated expression of CCL2 further recruits tumor-associated macrophages, thereby constructing an immunosuppressive microenvironment around CSCs." (PMID 41368628, 2025). "NSCLC cells also exhibit up-regulation of CTBP1, which stimulates CCL2 secretion, contributing to tumor-associated macrophage recruitment and polarization, and promoting NSCLC progression." (PMID 41154714, 2025). "Nevertheless, in tumors, CCL2 was shown to induce an increase in tumor-supporting TAMs (tumor-associated macrophages) and MDSCs (myeloid-derived suppressor cells)." (PMID 39857957, 2025). "The results mirrored those observed in global Ccl2−/− mice, hematopoietic loss of CCL2 significantly reduced tumor burden and decreased extravascular recMac accumulation compared to WT chimeras." (PMID 40630529, 2025). "The absence of TGF-β type 2 receptor in fibroblasts leads to increased CCL2 secretion and enhances tumor progression associated with TAM recruitment." (PMID 40890855, 2025). "It is a selective inhibitor of oncogenic transcription and can also affect the tumor microenvironment by targeting tumor-associated macrophages (TAMs) and reducing inflammatory chemokines such as CCL2." (PMID 39858036, 2025). "Tumor-associated macrophages (TAMs), comprising up to 50% of the tumor mass, are recruited via chemokine axes such as CCL2/CCR2, CX3CL1/CX3CR1, and CXCL12/CXCR4 and adopt an M2-like immunosuppressive phenotype, facilitating immune escape and angiogenesis." (PMID 41002423, 2025). "Of particular note, CCL2 secretion specifically by MSCs has been implicated in MDSC homing from the bone marrow to tumor sites." (PMID 41170853, 2025). "Parallel investigations should focus on evaluating OC’s impact on PAR-2-driven secretion of chemokines such as CCL2/MCP-1, which contribute to tumor-associated macrophage (TAM) recruitment and immune evasion." (PMID 40564985, 2025). "It was demonstrated that the CCL2/CCR2 axis is associated with tumor aggressiveness in DE-DLBCL by increasing M2 polarization rates, making it a potential therapeutic target." (PMID 40426926, 2025). "Secondly, elevated CCL2 levels recruit tumor-associated macrophages (TAMs), which secrete IL-6 and activate STAT3, further promoting immune modulation." (PMID 40087784, 2025). "Tumor-associated-macrophage recruitment and polarization is facilitated by mitochondrial fission, which causes cytosolic mtDNA stress and increases CCL2 secretion by cancer cells." (PMID 41276823, 2025). "CCL2 recruits monocytes and tumor-associated macrophages that promote angiogenesis and metastasis, particularly to the lungs." (PMID 41007766, 2025). "Tumour cells are able produce chemokine CCL2, which attracts MDSCs, Tregs, tumour associated macrophages and cancer associated fibroblasts into the primary tumour." (PMID 41373503, 2025). "MFA also recruits tumor‐associated macrophages through CCL2 and CCL5 signaling, fostering an immunosuppressive niche conducive to metastasis." (PMID 40755324, 2025). "Among the mediators of MC-OSCC interactions, CCL2 has been identified as a key chemokine associated with reduced tumor invasiveness." (PMID 40061903, 2025).
tumor (continued). "DRP1‐mediated mitochondrial fission presented in HCC promotes tumour‐associated macrophage infiltration by triggering intracellular mtDNA stress and increasing CCL2 release through the TLR9‐dependent NF‐κB signalling pathway." (PMID 40462487, 2025). "microRNA-206 can inhibit the induced expression of CCL2 in tumor-associated macrophages and cytotoxic T lymphocytes by regulating the Kruppel-like factor 4 (Klf4) transcription factor." (PMID 41341593, 2025). "MC38 and LLC1 Ccl2-deficient tumor cells showed reduced lung metastasis in both Ccr1- and Ccr2-deficient mice when compared to wild-type mice." (PMID 39566333, 2025). "Over the past decade, several CAFs-derived chemokines such as interleukin-6 (IL-6), C-X-C motif chemokine ligand 12 (CXCL12), and C-C motif chemokine ligand 2 (CCL2) have been implicated in the mechanisms driving tumor progression." (PMID 41408647, 2025). "CCL2/CCR2 recruits inflammatory monocytes that differentiate into tumor-associated macrophages (TAMs), often assuming immunosuppressive, pro-angiogenic phenotypes that blunt cytotoxic T-cell control." (PMID 41440526, 2025). "CCL2 is instrumental in attracting tumor-associated macrophages (TAMs) that adopt a pro-tumorigenic phenotype, supporting cancer cell survival, enhancing tumor cell invasion, and promoting angiogenesis." (PMID 39930476, 2025). "While N1 marker expression remained stable, Neu2 (differentiation end) exhibited mild up-regulation of N2-associated markers, including ARG1, VEGFA, and CCL2, consistent with an immunosuppressive, tumor-promoting phenotype." (PMID 40959269, 2025). "Tumor-associated macrophages (TAMs), derived from circulating monocytes recruited to tumor sites via chemotactic signals such as C-C motif ligand 2 (CCL2) and colony-stimulating factor-1 (CSF-1), are pivotal components of the tumor microenvironment (TME)." (PMID 40850976, 2025). "Concurrently, AKT signaling induces chemokines such as CCL2, promoting the recruitment of immunosuppressive cells like tumor-associated macrophages (TAMs) and myeloid-derived suppressor cells (MDSCs)." (PMID 40936705, 2025). "Mechanistic studies demonstrate that NF-κB activation induces tumor cells to secrete chemokines such as CCL2, which facilitates monocyte recruitment to tumor sites and their subsequent differentiation into tumor-associated macrophages (TAMs)." (PMID 40141137, 2025). "Experiments revealed that depletion of cathepsin S in tumors leads to reduction of CCL2 and tumor-associated macrophages, demonstrating the roles of cathepsin S in altering the cellular constitution of the TME and driving tumorigenesis." (PMID 41026370, 2025). "By inducing a senescence-associated secretory phenotype (SASP) and elevating cytokines such as TGF-β and CCL2, RT recruits M2-like tumor-associated macrophages (TAMs) and myeloid-derived suppressor cells (MDSCs)." (PMID 41440207, 2025). "Tumor-associated fibroblast (TAF)-derived CCL2 and downstream transcription factor Ets-1 are associated with TAF-induced fibroblast growth factor receptor 4 (FGFR4) upregulation in colorectal cancer cell lines." (PMID 40777019, 2025). "L1CAM-AS1-induced CCL2 secretion from HCC cells enhances M2 polarization of tumor-associated macrophages (TAMs)." (PMID 40536332, 2025). "For example, Tumor-associated macrophages (TAMs), attracted by tumor-derived chemokines like CCL2 and CSF-1, often adopt an M2-like phenotype, producing anti-inflammatory cytokines like IL-10 and TGF-β." (PMID 40739089, 2025). "Once monocytes reach the bone marrow, they can be reprogrammed into tumor-associated macrophages (TAMs) with osteoclast-activating properties, leading to CCL2 and IL-10 production and promoting bone resorption." (PMID 41010912, 2025). "Following over-expression of CCL2 mRNA, high levels of CCL2 recruit tumor-associated macrophages (TAMs) and reduce anti-tumor immunity." (PMID 41154428, 2025).
tumor (continued). "The analysis identified the most prominent and significantly altered cell clusters as Tumor-associated macrophages (TAMs) (Clusters 1, 2, and 3), characterized using macrophage markers such as Adgre1 (F4/80), Apoe, Lyz2, Ccr2, and Ccl2." (PMID 41321310, 2025). "It was revealed that MYC and BCL2 were associated with raised CCL2 expression by upregulating nuclear factor-kB in tumor cells and promoting M2 polarization." (PMID 40426926, 2025). "Androgen blockade or AR loss increases CCL2 production from both tumor cells and stromal compartments, enhancing CCR2+ monocyte influx and downstream STAT signaling, which subsequently accelerates tumor progression and dissemination." (PMID 41488638, 2025). "In GBM, tumor-derived chemokines such as CCL2 and CCL22 bind to CCR4 on Tregs and have been implicated in their selective recruitment to the tumor." (PMID 40867165, 2025). "The upregulated chemokines can attract a diverse range of innate and adaptive immune cells, for example, CCL2 attracts tumor-associated macrophages, CXCL10/11 attracts CD8+ T cells, CCL20 attracts dendritic cells, and CXCL5 attracts neutrophils." (PMID 40689422, 2025). "Preclinical evidence also indicated a more suppressive environment featured excessive myeloid suppressor cells, tumor-associated macrophages (TAMs), and tumor CCL2 secretion after incomplete RFA, which in turn hindered the anti-PD-1 immunotherapy." (PMID 40521175, 2025). "Conversely, CD10+ CAFs recruit tumor-associated neutrophils (TANs) via CCL2 secretion, accelerating lung metastasis." (PMID 40909292, 2025). "Cluster 1 contained genes significantly upregulated in AMPKα1/α2–deficient tumor-infiltrating Treg cells and included genes encoding chemokines (Ccl2, Ccl7, Ccl8), modulators of lipid metabolism (Cd36, Pparg, Lpl, Abca1), and glycolytic enzymes (Hk2, Hk3)." (PMID 40100289, 2025). "PTEN loss in tumor cells facilitates perivascular brain colonization and invasion and later increases secretion of the chemokine CCL2, which attracts myeloid cells, furthering metastatic proliferation." (PMID 40076927, 2025). "Elevated levels of CCL2 are associated with poor overall survival in several cancer types, as it functions as a tumor-promoting factor." (PMID 40806751, 2025). "Elevated CCL2/MCP-1 mirrors monocyte-mobilizing programs also implicated in tumor-associated macrophage biology, highlighting mechanistic overlaps between acute viral pneumonitis and cancer microenvironments." (PMID 41440526, 2025). "Hepatic infiltration and activation of MDSCs can be regulated by inflammatory chemokines (e.g., CXCL1 and CCL2) and cytokines (e.g., IL-6), tumor-associated fibroblasts, epigenetic factors, and gut microbiota during liver pathogenesis." (PMID 38397901, 2024). "ALKBH5 was found to recruit programmed death-ligand 1-positive tumor-associated macrophages and promote M2 macrophage polarization by inducing the secretion of CCL2 and CXCL10." (PMID 38872221, 2024). "Preclinical models suggest that blockade of CCL2 improves tumor control and suppresses tumor-associated macrophage accumulation." (PMID 38697618, 2024). "For instance, CCL2 has been reported to recruit Tregs, tumor-associated macrophages, as well as MDSCs." (PMID 39034411, 2024). "In the current study, SNPs rs1024610, rs1024611, and rs2530797 in CCL2 were significantly associated with the PR status, while rs3760396 was correlated with the Her2 status and tumor grade." (PMID 39703847, 2024). "During the progression of COAD, studies have shown that the expression levels of certain chemokines, such as CXCL9 and CCL2, are closely associated with the tumor’s invasive behavior and prognosis." (PMID 38791448, 2024). "The secretion of growth factors such as TGF-β and VEGF and cytokines such as CCL2 and IL-10 by tumor cells enables angiogenesis and recruitment of tumor-associated macrophages, promoting tumor growth and metastasis." (PMID 39407505, 2024).